IGF1 (insulin like growth factor 1)
Diseases named in the same sentence as IGF1 in open-access papers (continued):
Sharing a sentence is not in itself a finding about the gene and the disease.
cancer (continued). "Understanding the functional effects of IGF1 gene alternative splicing may reveal new molecular mechanisms of carcinogenesis and guide anti-cancer therapeutic strategies." (PMID 39796756, 2025). "Moreover, adipose tissue secretes various adipokines, including tumor necrosis factor (TNF)-α, interleukin (IL)−6, leptin, and insulin-like growth factor (IGF-1), which are thought to have pathological effects in various cancers." (PMID 40624408, 2025). "The disproportionately high prevalence observed may reflect referral bias, greater disease severity, and more intensive surveillance in this tertiary-center cohort, which also reported elevated GH and IGF-1 at cancer diagnosis." (PMID 41293738, 2025). "Cancer-associated fibroblasts (CAFs) express and secrete signalling proteins which stimulate cancer cell proliferation, including insulin-like growth factor-1 (IGF-1), hepatocyte growth factor (HGF), stromal-cell-derived factor-1 (CXCL12), and a range of fibroblast growth factors (FGFs)." (PMID 39859271, 2025). "In fact, although there are no direct studies linking IF to reduced cancer risk in humans, its effect has been explored through its impact on tumor-related factors, such as insulin, glucose, IGF-1, leptin levels, adiponectin and weight loss." (PMID 39940361, 2025). "F1 demonstrates unique immunomodulatory properties through NK cell activation via IGF-1-dependent mechanisms, while Rg5 and Rk1 exhibit broad-spectrum cytotoxicity across multiple cancer types including breast cancer, cervical cancer, and hepatocellular carcinoma." (PMID 41155644, 2025). "FMD may help prevent cancer, possibly by acting on metabolic pathways such as reducing IGF-1, activating AMPK, and/or affecting nutrient-sensing mechanisms that play a critical role in regulating cell proliferation, death, and survival." (PMID 39940361, 2025). "Furthermore, emerging evidence suggests that MTF's effects on insulin and IGF‐1 signaling extend beyond cancer cells to impact the tumor microenvironment." (PMID 39969135, 2025). "Similarly, global transcriptomic and biochemical analyses indicate that the activity of the insulin/IGF‐1–AKT–mTOR pathway is diminished in the cachectic muscle of cancer patients and animal models." (PMID 39764565, 2025). "MSC-mediated protection against apoptosis has been reported in other cancer types and is often attributed to the secretion of anti-apoptotic cytokines such as insulin-like growth factor 1 (IGF1) and leptin, or via exosome-mediated delivery of survival signals such as miR-410, miR-21 and miR-34a." (PMID 40940728, 2025). "The effects of fasting on cancer are mediated by several key molecular pathways, including the IGF-1, mTOR, AMPK, and autophagy pathways, each of which plays a distinct role in regulating metabolism, cell growth, and survival under nutrient-deprived conditions." (PMID 39940361, 2025). "Theoretically, cancer patients may benefit from decreased IGF-1 levels, given IGF-1’s role as an anabolic hormone involved in oncogenic signaling pathways." (PMID 40566597, 2025). "Low levels of IGF‐1 not only reduce proliferative capacity of liver cells but also heighten their sensitivity to inflammatory and tumor growth factors, thereby facilitating cancer cell formation and proliferation." (PMID 40060195, 2025). "Increased expression of IGF-1 has been described in association with increased risk of different type of cancer although the molecular mechanisms are not completely elucidated." (PMID 39555455, 2024). "Furthermore, the IGF-1R accumulates intracellularly at the Golgi in these aggressive cancer cell lines, and drug-induced disruption of the Golgi abrogates IGF-1-mediated activation of SHC." (PMID 39608716, 2024). "Furthermore, low IGF-1 level suggests GH deficiency in screening of short stature in chlidren, while high IGF-1 levels is reportedly related cancer or mortality." (PMID 39403490, 2024).
cancer (continued). "Therefore, decreased synthesis of IGFBP-1 increases the level of biological active free IGF-1, stimulating cancer growth." (PMID 38392069, 2024). "Second, insulin and insulin-like growth factor-1 are known to be involved in cancer progression." (PMID 38523829, 2024). "Indeed, there is increased production of growth factors, like insulin and insulin-like growth factor 1 (IGF-1), which promote cell growth and division and higher levels of sex hormones, particularly estrogen, which can influence cancer risk." (PMID 38541801, 2024). "CR and, in particular, insulin/IGF1 inhibition slows down the cell cycle and thus global tumor growth, but at the same time attenuates responsiveness to innate immune pathways that would induce cancer stem-cell clearance, favoring their persistence." (PMID 38280853, 2024). "Additionally, the extended fasting time in TRE regimens is expected to reduce the exposure to cancer-promoting growth factors like insulin and IGF-1." (PMID 39458471, 2024). "IGF-1 is a potent mitognic and anti-apoptotic factor, which is involved in cancer growth." (PMID 38392069, 2024). "In mouse models, the FMD synergistically improved the cancer-fighting impact of endocrine therapies, such as tamoxifen and fulvestrant, by significantly lowering systemic levels of IGF-1, insulin, and leptin, and impeding AKT–mTOR signaling pathways through the increased expression of EGR1 and PTEN." (PMID 38321992, 2024). "In any case, it is tempting to hypothesize that life-long exposure to GH and IGF1 excess may favor the progression of a malignant tumor leading to death many years later, often when the acromegalic disease is under control." (PMID 38214852, 2024). "Suppressor of IGF1 signaling plays essential roles in cancer therapy." (PMID 39042294, 2024). "Therefore, it will be of value to explore the candidacy of IGF-1 as a prophylactic target in both cancer and Küry−Isidor syndrome." (PMID 38969833, 2024). "Furthermore, the activation of the insulin-like growth factor (IGF)-1/IGF 1 receptor (IGF-1R) system induces stimulatory effects via GPER in highly malignant neoplasms such as mesothelioma and lung tumors." (PMID 38476263, 2024). "TP63 and IGF1 were also involved in some cancer-related pathways." (PMID 39157347, 2024). "Thereby IGF1/IGF1R alteration usually occurs in cancers and metabolic disorders." (PMID 39867883, 2024). "The protective effect against cancer associated with a non-functioning insulin/IGF1 pathway was confirmed in Caenorhabditis elegans." (PMID 38255007, 2024). "The role of IGF-1 as a critical growth and survival factor in human cancers is well-established." (PMID 39273251, 2024). "Moreover, insulin binding to the insulin-like growth factor receptor (IGF-1) on the cell surface promotes cell proliferation and subsequently engenders the development of various malignant tumors." (PMID 38554189, 2024). "Insulin acts as a powerful growth factor that can promote cell growth and may induce cancer, either directly or through insulin-like growth factor-1 (IGF-1)." (PMID 39684895, 2024). "Some of the suggested mechanisms for physical activity protective effect against cancer are regulation of interleukin-6 (IL-6) activity, reduction in insulin growth factor-1 (IGF-1) levels, mitochondrial function enhancement in apoptosis of cancer cells, and epigenetic alterations." (PMID 38768241, 2024). "It is tempting to speculate that local IGF1 secretion may also serve as a ferroptosis defense mechanism for cancer stem cells." (PMID 38802843, 2024). "IGF-1 has been hypothesized to play a crucial role in mediating DTCs' interaction with the bone microenvironment in various types of cancers e.g., neuroblastoma, breast cancer and prostate cancer." (PMID 39497943, 2024). "Expression was evaluated across 34 cancers, identifying immune DEGs IGF1 and AVPR1A." (PMID 38167455, 2024).
cancer (continued). "Recent literature shows that the RAGE pathways may act as novel facilitators of IGF1 action in the protumorigenic crosstalk between cancer cells and the microenvironment." (PMID 38892104, 2024). "Additionally, it has been found to alter genetic expression to improve pancreatic beta cell function, markers of aging and cancer, and insulin-like growth factor 1 (IGF-1)." (PMID 38201992, 2024). "IGF-1, for example, can be produced by activated stromal fibroblasts and may contribute to cancer cell growth." (PMID 38920688, 2024). "Combining multiple agents and fine-tuning selective inhibitors which spare IR while impairing the pro-cancer functional significance of IGF-1 might be accomplished by further examining the structural differences and binding peculiarities of IGF-1R and IR." (PMID 39273251, 2024). "The effect of C#1 is attributed to a reduction in both the endo- and endocrine activities of the GH/IGF1 axis with the potential to inhibit GH-driven cancer growth, although the same compound appeared to have DHFR inhibitory effects in vitro as well and acts as an antifolate." (PMID 39459020, 2024). "The scientific literature suggests that this may be the result of IGF-1 promoting neoplastic angiogenesis, metastasis, and cancer cell proliferation." (PMID 38455769, 2024). "The association of circulating levels of IGF-1, IGFBPs, and insulin also supports their roles in cancer but is not always consistent with the molecular data." (PMID 38928185, 2024). "Among the top downregulated 50 genes, there were other cancer relevant genes such as cell cycle associated (CCNF1, CCNB1, ZWINT), cancer signaling (STK32B, IGF1, FLT1) and splicing associated (HNRNPM, HNRNPU, SRSF1) genes, which are active areas to investigate further." (PMID 38200580, 2024). "However, the role of IGF2 in cancer progression is certainly less characterized when compared to IGF1 and insulin." (PMID 36672737, 2023). "Previous study has shown that SKA2 co-localizes and interacts with glucocorticoid receptor (GR), and enhancing the cancer cell proliferative response to IGF-1 exposure 8, suggesting that SKA2 should be capable of regulating its target genes to augment cancer cell progression." (PMID 36860919, 2023). "Phosphorylation of FLNA at S2152 was shown to occur by mTOR and by IGF-1 in cancer cells." (PMID 37457922, 2023). "However, the introduction of radiotherapy was found to promote the cellular export of miR-603 in the form of EV from cancer cells and this led to the de-repression of both IGF1 and IGFR1." (PMID 36674525, 2023). "For these reasons, inhibitors of IGF-1/R have been assessed as therapies for various cancers in clinical trials, although, as of 2023, only two—ceritinib and teprotumumab—have been approved by the United States Food and Drug Administration (FDA) for any indication." (PMID 37240591, 2023). "Impaired nuclear and Golgi IGF-1 signaling inhibits growth factor-induced cancer cell migration." (PMID 36831629, 2023). "IGF-1 may contribute to pain pathogenesis in cancer by upregulating the expression and function of TRPV1." (PMID 37242543, 2023). "This cancer-promoting effect may be mediated by systemic effects of insulin/insulin-related growth factor-1 (IGF-1) and inflammatory signaling." (PMID 37346909, 2023). "The relationship of post diagnostic serum IGF‐1 levels and cancer survival has not been well studied." (PMID 37269192, 2023). "In contrast with our finding, a meta-analysis of 10 studies that included 9,415 CRC cases and 14,179 controls in Caucasians and Asian population showed that the IGF1 rs35767C>T polymorphism was associated with decreased susceptibility to CRC in Caucasians, and has a protective effect against cancer." (PMID 37284192, 2023). "Moreover, we found an association between these biomarkers and IGF-1/IGFBP3, which enhances their credibility as biomarkers for cancer detection in high-risk tumors." (PMID 37108716, 2023).
cancer (continued). "IGF-1 could be also produced by PCa cells and is a key regulator of cancer growth through the MAPK and PI3K enzymes, and these signaling pathways are blocked by antibiotics." (PMID 36675055, 2023). "Our study also identified an association between PCSK9 inhibitors and lower IGF‐1, which may indicate a decrease in cancer risk, since IGF‐1 is implicated in the growth and proliferation of cancer cells." (PMID 37208559, 2023). "IGF‐1R is upregulated in most malignant tumors, and its combination with the ligands IGF‐1 or IGF‐2 can activate the PI3K/AKT and Ras/Raf/MEK/ERK/MAPK signaling pathways, thereby promoting tumor proliferation, differentiation, and migration and playing a role in fine‐cell apoptosis inhibition." (PMID 36994237, 2023). "The potential etiology of the different types of cancer may be due to the different influences of rapidly increasing levels of estrogen, progesterone, insulin-like growth factor-1 (IGF-1), and leptin during pregnancy." (PMID 37179417, 2023). "Finally, in addition to TGF-β, insulin-like growth factor-1 (IGF-1) can also promote cancer proliferation and survival, inducing EMT that contributes to tumor migration, invasiveness, and metastasis." (PMID 37371856, 2023). "Studies have demonstrated that low IGFBP-3 and high IGF-1 and IGFBP-2 levels are associated with high cancer risk, poor prognosis, and tumor metastasis in several cancers, including CRC, breast cancer, and prostate cancer; however, these findings remain controversial and can be population specific." (PMID 38137390, 2023). "In contrast to serum IGF-1, IGF-1R activity, especially cytoplasmic and nuclear IGF-1R expression, has been proven to promote radiotherapy resistance and enhance the risk of biological cancer recurrence." (PMID 36831629, 2023). "While genetic IGF-1 deficiency in humans is associated with shortened lifespan, certain genetically modified mouse models with IGF-1 deficiency show lifespan extension due to its anti-cancer growth action." (PMID 37495893, 2023). "Proteins belonging to the insulin/IGF-1 pathway are also deregulated in cancer." (PMID 37895144, 2023). "Therefore, in this study, we also looked for changes in insulin/IGF-1, mTOR, NF-B, and Sirtuin signaling pathways, as well as signaling pathways related to cancer, in relation to the increase in the level of CR." (PMID 36757838, 2023). "Consequently, inhibitory reagents targeting IGF-1/IGF-1R have been developed to limit cancer development." (PMID 36831629, 2023). "It has been reported that cancer patients with cachexia exhibit lower levels of circulating IGF1." (PMID 37217930, 2023). "Increased levels of unbound insulin-like growth factor-1 (IGF-1) promote cancer formation." (PMID 37048059, 2023). "Different biological mechanisms are proposed to explain the adiposity-cancer link including altered sex hormone metabolism, increased insulin levels and the bioavailability of insulin-like growth factor 1 [IGF1], adipokine pathophysiology, and systemic inflammation." (PMID 37993940, 2023). "Additionally, CAFs can stimulate the uptake of glucose by cancer cells through the secretion of growth factors such as insulin-like growth factor 1 (IGF-1) and transforming growth factor beta (TGF-β)." (PMID 37446193, 2023). "Therefore, clarifying the complex IGF1 signaling pathway in cancer sheds light on therapeutic strategies for directly and indirectly targeting the IGF1 axis." (PMID 36774408, 2023). "We show fasting’s ability to increase CBIs’ antitumour effects to depend on the reduction in circulating insulin, insulin-like growth factor-1 and leptin, which blunts the expression of enzymes from the cholesterol biosynthesis pathway and enhances cholesterol efflux from cancer cells." (PMID 37907500, 2023). "Furthermore, a high-fat diet promotes excess body adiposity, which can lead to cancer development by the mechanisms involved in elevated insulin and insulin-like growth factor 1 (IGF-1) secretion." (PMID 35406496, 2022).
cancer (continued). "The anti-cancer effects of antioxidants in interaction with IGF-1 signaling and pathway involving target-of-rapamycin (TOR) may control cell growth." (PMID 35232437, 2022). "The demonstrated significant reduction in the proliferative marker IGF-1, vital to tumour development and progression, may be hypothesis-generating for additional benefits of IF for cancer patients." (PMID 36235868, 2022). "Previously, insulin was often regarded as an alternative factor of IGF-1 in cancer development." (PMID 35252207, 2022). "This high frequent expression might be attributed to the role of the growth hormone/IGF-1 axis in oncogenesis and progression of cancer." (PMID 35366286, 2022). "This phenomenon further confirms the powerful effects of GH/IGF-1 on the promotion of cancers." (PMID 35855334, 2022). "The increased cancer incidence among taller individuals could relate to early-life exposure to hormones such as insulin-like growth factor 1 (IGF-1) or the increased number of cells in taller individuals." (PMID 35302490, 2022). "The impact of low IGF1 concentrations on cancer risk, on the other hand, has not yet been systematically addressed." (PMID 35626664, 2022). "Moreover, pathway analyses showed that the DEGs were involved in multiple cancer-associated pathways, such as TGF-β, mTOR, IGF-1, NF-κB and PTEN pathways in LUAD." (PMID 36446361, 2022). "Recently, Sarah Riis and colleagues reported a conserved Akt/GSK-3β/Nrf2/BNIP3 pathway for regulating mitochondrial morphology and dynamics in mouse embryonic fibroblasts and cancer cells, which provides mechanistic clues for IGF-1-dependent BNIP3 transcription during differentiation." (PMID 35334906, 2022). "Existing evidence indicated that these foods containing high-glycemic carbohydrates and saturated and trans-fatty acids can lead to cancer development and tumor growth by the mechanisms involved in elevated insulin and IGF-1 secretion and proinflammatory status." (PMID 35406496, 2022). "We also found that the hormone-sensitive cancer status was significantly associated with non-cancer traits, e.g., IGF-1 and height signifying the suggestive role of these non-cancer traits in the complex biology of cancer." (PMID 35729236, 2022). "In light of the fact that childhood and adolescence are marked by rapid growth, consistent exposure to high levels of circulating IGF-1 may set the stage for cancer development and progression in later life." (PMID 35334890, 2022). "Moreover, elevated HbA1c levels influences cancer progression through an increase in the levels of insulin, insulin-like growth factor-1 (IGF-1), and inflammatory cytokines in circulation." (PMID 35836264, 2022). "Specifically, higher plasma levels of IGF-1 were reported previously to be associated with malignancy, whereas deficiencies of growth hormone and IGF-1 were related to the absence of cancers." (PMID 35366286, 2022). "Accordingly, LS cells, which are exposed to lifetime low IGF1 dosages, might be less prone to become senescent or to efficiently handle a stress response—with ensuing cancer protection." (PMID 36291127, 2022). "This phenomenon may be explained by different pathological conditions: IGF-1 is overexpressed in cancer cells as a promitogenic molecule, while under the diabetic condition, spinal IGF-1 signaling is much below the normal range." (PMID 35401920, 2022). "The possible mutagenic effects of insulin or insulin analog and increased levels of IGF-1 might be the potential biological plausibility for the increase risks of cancers." (PMID 35222270, 2022). "EGCG is identified as a strong modulator of IGF-1/IGF1R signaling in cancer diseases." (PMID 35401920, 2022). "A prevalent hypothesis is that GH stimulates cancer stem cell growth, while GH/IGF1 drives epithelial-to-mesenchymal transition and metastasis." (PMID 35966052, 2022).